U3 (Small nucleolar RNA U3 )
Synonyms: LOC124904802
Gene: Small nucleolar RNA gene on chromosome 19 (49,949,316 to 49,949,527, reverse strand). Ensembl gene ENSG00000221125.
Gene Ontology:
Biological process: RNA processing
Cellular component: nucleolus
Homologues: Orthologues: chimpanzee U3 (99% identical), macaque U3 (93% identical). Paralogues in human: SNORD3P1 (74% identical), U3 (74% identical), U3 (73% identical), U3 (72% identical), U3 (71% identical), SNORD3E (71% identical), SNORD3G (71% identical), U3 (70% identical), SNORD3D (70% identical), U3 (69% identical), U3 (68% identical), U3 (67% identical), and 11 more.